HK2 (hexokinase 2)
Diseases named in the same sentence as HK2 in open-access papers (continued):
Sharing a sentence is not in itself a finding about the gene and the disease.
cancer (continued). "Recently, hexokinase 2 (HK2), an important enzyme for cancer growth, has been reported as an AHR target gene that modulates AHR activity by promoting AHR promoter demethylation." (PMID 37696456, 2023). "All in all, HK2 plays a critical role in oncogenesis in several ways and is a desirable drug target for cancer therapy." (PMID 38001865, 2023). "Despite this, HK2 is induced in other tissues in various diseases and has been studied most thoroughly in several types of cancer." (PMID 37529037, 2023). "18F-Fluorodeoxyglucose (FDG) is a glucose analog that is transported via glucose transporters into the cancer cells followed by hexokinase 2 (HK2)-mediated phosphorylation." (PMID 38001865, 2023). "Among these different HKs, HK2 was upregulated in a variety of cancers and played a key role in the development of Warburg." (PMID 37663261, 2023). "The inhibition of HK2 has been shown to impair glycolysis and lead to decreased cell proliferation and tumor growth in various cancer types." (PMID 37233659, 2023). "Physiologically, p63 affects metabolism through the direct transactivation of the enzyme hexokinase 2, and subsequently controls the proliferation of epithelial cells; nonetheless, its role in cancer metabolism is still largely unclear." (PMID 37946250, 2023). "HK2, one of the key metabolic enzymes, catalyzes the irreversible rate-limiting step of glycolysis and accelerates aerobic glycolysis and cancer progression." (PMID 37019900, 2023). "Compared to normal cells, cancer cells show elevated expression of HK2, which is responsible for the increased glucose flux to some extent in cancer cells, making HK2 an attractive pharmacological target for cancer therapy." (PMID 36984785, 2023). "CircRNA also regulates other enzymes to influence the development of malignant tumours besides the glycolytic rate-limiting enzymes HK2 and PKM2." (PMID 37599427, 2023). "In PET, 18F-2-deoxyglucose (18F-2-DOG) is converted to 18F-2-DOG-6-P by VDAC bound to HK2, allowing the monitoring of cancer evolution in patients." (PMID 38139462, 2023). "Inhibition of the activity of HK2 enzyme by arsenic is a key mediator of arsenic-induced apoptosis in cancer cells." (PMID 36984785, 2023). "It has been found that HOTAIR upregulation promotes hexokinase 2 (HK2) expression, a protein that plays a pivotal role in energetic cancer metabolism." (PMID 37189687, 2023). "Among these up-regulated key enzymes, HK2 is one of the key factors involved in the development of a variety of human cancers." (PMID 37347113, 2023). "Hexokinase 2 (HK2) is a rate‐limiting enzyme of glycolysis that is highly expressed in many human cancers and promotes proliferation, angiogenesis and glycolysis." (PMID 37539493, 2023). "KRAS4A can interact with Hexokinase 1 and relieve glucose-6-phosphate-dependent allosteric inhibition of Hexokinase 143 possibly enabling Hexokinase 1 to be a stronger driver of glucose consumption than Hexokinase 2 in certain cancers." (PMID 36697489, 2023). "Treatment with the HK2 inhibitor 3-bromopyruvate reduces the aerobic glycolysis flux in cancer cells and destabilizes the redox state of the cancer cells." (PMID 37762231, 2023). "Recently, HK2-targeted therapy has displayed beneficial effects in suppressing cancer cell growth in vitro and eradicating tumors in animals." (PMID 37019900, 2023). "Hexokinase 2 (HK2), which catalyzes the initial rate-limiting and irreversible step of glycolysis reaction, exerts a key role in altered metabolism in various cancers." (PMID 37019900, 2023). "Human miR-143 on chromosome 5 inhibits the glycolytic enzyme HK2 and upregulates aerobic glycolysis in cancer cells." (PMID 38234430, 2023). "Targeting HK2 inhibits cell proliferation and shifts the metabolic profile of cancer cells from glycolytic to oxidative phosphorylation (OXPHOS)." (PMID 36768924, 2023).
cancer (continued). "There was also downregulation of hexokinase 2 (HK2) expression involved in the rapid activation of glycolysis in cancer cells." (PMID 37834191, 2023). "There was also a reduction in hexokinase 2 (HK2) expression, which is involved in the rapid activation of glycolysis in cancer cells." (PMID 37834191, 2023). "Previous studies reported that Akt and HK2 are overexpressed in cancer cells and that there is a positive correlation between activation of the PI3K/Akt/mTORC1 pathway and HK2 expression." (PMID 36232922, 2022). "HK2 is active at very low glucose concentrations due to its low Km, thus allowing the cancer cells to maintain an active glycolysis independently of the glycemia to meet the important energy and biosynthesis needs for their multiplication." (PMID 35055105, 2022). "The central carbon metabolism in cancer pathway (ecb05230, e.g., LDHB, HK2) controls cancer metabolic adaptations through aerobic glycolysis, elevated glutaminolysis, dysregulated tricarboxylic acid cycle and pentose phosphate pathways." (PMID 36553455, 2022). "A large body of evidence suggests that HK2 is fundamental in modulating cancer glycolysis, and several compounds have shown promise in suppressing cancer growth by specifically inhibiting this protein." (PMID 35563663, 2022). "HK2 induction in most in cancer cells couples metabolic and proliferative activities, and its genetic ablation inhibits malignant growth in mouse models." (PMID 35953860, 2022). "Specifically, hexokinase type II (HK2) is upregulated more than 100-fold in proliferating cancer cells compared to normal cells." (PMID 36077352, 2022). "Although all three Hk2 mutations were also judged pathogenic per the FATHMM algorithm, the molecular connection between these mutations and cancer progression remains undefined." (PMID 35235554, 2022). "The ability of miR-125b-5p to target the HK2 gene to affect cellular glycolysis has been reported to a lesser extent in recent years, but almost all studies have been related to cancer." (PMID 36059492, 2022). "Their localization was shown to contribute to the maintenance of intracellular and mitochondrial Ca2+ homeostasis, HK2 displacement promoting Ca2+-dependent death of cancer cells." (PMID 35890106, 2022). "The two most abundantly expressed isoenzymes HK1 and HK2 are critical for maintaining an elevated rate of glycolysis in cancer cells." (PMID 36304460, 2022). "Oleanolic acid, a triterpenoid component found in vegetable oils and the leaves or roots of Oleaceae family plants, can suppress cancer cell growth by reducing the expression and activity of HK2 and PFK1 in human gastric carcinoma cells." (PMID 36339566, 2022). "HK2 is a vital rate-limiting enzyme in glycolysis and is usually overexpressed in cancer cells, resulting in activated glycolysis." (PMID 36276638, 2022). "When circPVT1 is upregulated, miR-106a-5p activity is inhibited, leading to increased expression of HK2, which promotes cancer development." (PMID 34754096, 2022). "Several studies show that the HK2 is also important for the glucose transfer to these branching pathways in cancer cells." (PMID 35265223, 2022). "These molecules all target HK2 in many in vitro and in vivo tumor models, detach it from mitochondria, and elicit cancer cell death." (PMID 36230492, 2022). "To further understand the role of HK2 in cancer progression, we analyzed the transcriptional expression of HK2 in TCGA-associated cancers using the online GEPIA database." (PMID 35265223, 2022). "All of these studies in cancer disease confirm that miR-125b-5p binds to the 3’UTR of HK2 and affects the efficiency of cellular glycolysis." (PMID 36059492, 2022). "In fact, HK2 overexpression has been consistently reported in numerous types of cancer, including hepatocellular carcinoma, breast, colorectal, gastric, and lung cancer." (PMID 35890106, 2022).
cancer (continued). "While HK1 is widely and constitutively expressed, HK2 is selectively expressed during embryogenesis and in cancer where it has been shown to induce proliferation and inhibit cell death." (PMID 35902556, 2022). "Previous studies have demonstrated that HK2 was involved in multiple cancerous stages, including initiation, maintenance, growth, and metastasis in various cancers 8-11." (PMID 35711830, 2022). "Novel HK2 inhibitors, such as benserazide and benitrobenrazide, have also shown effects in cancer therapy." (PMID 36230492, 2022). "To circumvent this limitation, we recently developed a metabolically active Huh7-derived cell line (Huh7-GCK+/HK2−) by replacing the cancer-type hexokinase HK2 by GCK." (PMID 35055105, 2022). "HK2 is highly expressed in various cancers and is connected to poor pathological stage and prognosis." (PMID 36411480, 2022). "HK2 had been explored as a major player in helping maintain the highly malignant state in many types of cancer." (PMID 35498426, 2022). "Overexpression of HK1 and HK2 in cancer cells has been previously reported, and HK1 overexpression is a poor prognostic marker in colorectal cancer." (PMID 36497226, 2022). "In contrast, deletion of the HK2 gene can significantly inhibit the proliferation of cancer cells in animal models." (PMID 35982398, 2022). "Several studies have shown that systemic inhibition of HK2 can safely and effectively block cancer growth." (PMID 36230492, 2022). "Here, the authors show that hexokinase 2 can contribute to the metastatic spread of cancer cells independently of its glycolytic function via inhibiting the activity of GSK3β, which in turn elevates the protein levels of the EMT transcription factor SNAIL." (PMID 35173161, 2022). "In most cancer cells, the HK2 was found upregulated; thus, this explains the high rate of metabolism in cancer cells." (PMID 35265223, 2022). "HK2 expression, on the other hand, is elevated in cancer cells to boost glucose flow into multiple metabolic pathways." (PMID 36358687, 2022). "Recently, increasing evidence has indicated that elevation of Hexokinase 2 (HK2) plays an important role in several cancers on regulating cell motility and growth." (PMID 35953860, 2022). "In cancer cells, there are three committed steps in glycolysis that are catalyzed mainly by HK2, phosphofructokinase 1 (PFK1), and PKM2." (PMID 36046646, 2022). "HK2‐induced ACSL4 led to FAO for the maintenance of stemness and self‐renewal in liver CSCs, which identified a previously uncharacterized molecular mechanism for HK2 in human cancer." (PMID 35603967, 2022). "Hexokinase 2 expression is markedly induced in cancer cells and contributes to cancer cell metabolism." (PMID 35173161, 2022). "Overexpression of hexokinase 2 (HK2) and glucose transporter 1 (GLUT1) is associated with chemoresistance in cancer." (PMID 36359211, 2022). "HK2 was found to be critical for cancer initiation in mouse and human, and its expression level has prognostic value for human breast cancer patients." (PMID 36712976, 2022). "Hexokinase 2 (HK2) is the major bound hexokinase isoform expressed in cancers that exhibit a “Warburg effect”4." (PMID 36335239, 2022). "In many hexokinase 2 (a key enzyme of aerobic glycolysis) overexpressed malignant tumors, lonidamine, 3-bromopyruvate (3-BrPA) and 2-deoxy-D-glucose (2-DG) have been used as effective hexokinase inhibitors." (PMID 35326612, 2022). "HK2 has been reported to be related to the occurrence and migration of a variety of malignant tumors and regulate physiological processes." (PMID 35719058, 2022). "While positive HK2 expression usually promotes cancer cells survival, silencing or inhibiting this enzyme has been found to improve the effectiveness of anti-cancer drugs and even result in cancer cell death." (PMID 35269760, 2022).
cancer (continued). "HK1 is widely expressed in numerous organs, and HK2 expression is significantly upregulated in cancer cells, promoting glucose uptake and participation in multiple metabolic pathways." (PMID 36230492, 2022). "HK2 is involved in cellular metabolism, promoting glucose uptake in cancer cells as a carbon source for aerobic glycolysis." (PMID 34754096, 2022). "These include downregulation of HK2 in cancers compared with normal samples, such as LAML, OV, TGCT, and THYM." (PMID 35265223, 2022). "ABAT and HK2 have been reported to play crucial roles in cancer metabolism, progression, and therapeutic resistance of cancers." (PMID 35615380, 2022). "HK-2 is a highly bound hexokinase isoform that is commonly overexpressed in human cancers involving the activation of aerobic glycolysis, including HCC." (PMID 36506561, 2022). "In contrast, HK2, which has been shown to bind to the mitochondria in some cancer cell lines, was found to be in the cytosol and membrane fractions." (PMID 35902556, 2022). "We demonstrated that FGFR-TKI treatment response/resistance in cancer cells visualized by 18F-FDG PET imaging was correlated with FGF/FGFR signaling-mediated glucose metabolism via mTOR/HK2." (PMID 36168616, 2022). "Mechanistically, for the first time, we revealed that FGFR inhibition suppressed HK2 gene transcription via inhibiting mTOR in FGFRi-sensitive in vitro and in vivo cancer models with different FGFR1-4 anomalies." (PMID 36168616, 2022). "The HK2-mediated Warburg effect is essential for cellular transformation and growth in many cancer types." (PMID 36497226, 2022). "This ubiquitylation confers to HK2-dependent apoptosis resistance, enhanced glycolysis, and reduced reactive oxygen species generation, ultimately leading to cancer stem cell (CSC) self-renewal and tumor progression." (PMID 35136173, 2022). "One of the anti-cancer treatment strategies connected with the glycolysis pathway is targeting the enzyme HK2, which converts glucose into G6P and is responsible for the first step of glycolysis." (PMID 35628385, 2022). "Preclinical studies showed that 3-BP inhibits HK2 and is a promising anti-cancer drug targeting glycolysis." (PMID 35628385, 2022). "More importantly, targeting HK2 inhibitors can reverse B7-H3-induced increase in aerobic glycolysis and B7-H3-endowed chemoresistance of cancer cells." (PMID 36778600, 2022). "HK2 is barely expressed in normal cells; therefore, its systematic knockdown selectively targets cancer cells." (PMID 36230492, 2022). "Recent findings demonstrated that HK2 elicits multiple key steps responsible for cancer progression and resistance to current therapies." (PMID 35260660, 2022). "Previously, benitrobenrazide (BNBZ) was characterized as a potent HK2 inhibitor with good anti-cancer activity in mice, but the effect of its trihydroxy moiety (pyrogallol-like) on inhibitory activity and some cellular functions has not been fully understood." (PMID 35269760, 2022). "In conclusion, our first pan-cancer analysis of HK2 showed that the expression of HK2 in most tumors was different from that in normal tissues, and was statistically correlated with clinical prognosis and immune cell infiltration across multiple tumors." (PMID 36335239, 2022). "HK1 is generally expressed in most adult tissues, whereas HK2 is highly expressed in many fetal tissues and cancer cells." (PMID 36192599, 2022). "An increase in HK2 expression and activity is a critical determinant of the accelerated glucose metabolism in cancer cells." (PMID 35173161, 2022). "Some glycolysis suppressors targeting HK2 have been used to treat cancer (Mathupala, Ko & Pedersen, 2009)." (PMID 36193432, 2022).
cancer (continued). "Our first pan-cancer study offers a relatively comprehensive understanding of the roles of HK2 in different tumors." (PMID 36335239, 2022). "Studies have found that HK2 is overexpressed in many cancer types, and that the inhibition of HK2 expression can inhibit cancer cell proliferation." (PMID 35184747, 2022). "Cancer cells promote the primary step in glucose metabolism by boosting glucose absorption and generating high-level expression of hexokinase 2 (HK2), which is already expressed in normal cells." (PMID 36358687, 2022). "Hexokinases 2 (HK2) is a member of the hexokinases, linking with malignant tumor growth and distant metastasis." (PMID 34758823, 2021). "Although previous studies have suggested multiple roles for HK2 in cancer cell chemoresistance, we demonstrated that HK2 mediates oxaliplatin resistance by stabilizing Twist1." (PMID 34378321, 2021). "Previous results showed that HK2 was highly expressed in cancer tissues, and the expression of p-mTOR was decreased in BC cells when HK2 was silenced." (PMID 34345220, 2021). "For instance, the selective HK2 inhibitor Benitrobenrazide binds directly to HK2, blocks glycolysis, and induces apoptosis in HK2-overexpressing cancer cells." (PMID 34858863, 2021). "The results revealed that HK2 expression was elevated in most cancer tissues (including CC) compared with normal tissues." (PMID 34858863, 2021). "The results showed that the expression of HK2 in metastatic cancer tissues was higher than that in healthy tissues." (PMID 34378321, 2021). "In this study, we report that ETV4 is a critical transcription factor for metabolic rewiring in cancer cells, it promotes the transcription of hexokinase 2 (HK2) and lactate dehydrogenase A (LDHA), two enzymes indispensable for efficient glycolytic flux." (PMID 34052833, 2021). "HK2 induction in cancer is strictly intertwined with several pathways and factors, the deregulation of which drives neoplastic progression." (PMID 33946854, 2021). "The RTK, epidermal growth factor receptor (EGFR), and glycolytic protein hexokinase-2 (HK2) influence cell growth and the overexpression of both have been linked to more invasive and aggressive cancers." (PMID 34748597, 2021). "Human hexokinase 2 is an essential regulator of glycolysis that couples metabolic and proliferative activities in cancer cells." (PMID 33753739, 2021). "FDA-approved orphan drug 3-bromopyruvate which blocks glycolysis in cancer cells by inhibiting HK2 enzymatic activity has shown promising results in HCC patients." (PMID 34831316, 2021). "Anticancer therapeutics that target cancer growth will have to specifically inhibit HK2 and avoid interactions with HK in normal tissues." (PMID 33187984, 2021). "Multiple studies have shown that glycolytic enzymes such as hexokinase 2 (HK2), which is involved in the first rate-limiting step of glycolysis, are associated with poor prognosis in several cancer types." (PMID 33498721, 2021). "Once HK2 is deleted, the glycolytic flux and the proliferation of cancer cells have been inhibited with increased susceptibility to apoptosis induced by hypoxia." (PMID 34368116, 2021). "Hexokinase 2 (HK2) is a glycolytic enzyme that catalyzes the first committed step in glucose metabolism, and its expression is markedly induced in cancer cells by multiple mechanisms." (PMID 34174908, 2021). "Cancer cells cause changes in the expression of genes that code HIF-1, hexokinase 2 (HK2), phosphoglucose isomerase (PG), glyceraldehyde 3-phosphate dehydrogenase, and glucose transporters that are involved in the hypoxic conditions within tumors." (PMID 34439338, 2021). "Previous studies showed that HIF-1α involved in cancer cell metabolism by regulating HK2, GLUT1, and others." (PMID 34238918, 2021). "Many cancers fuel their rapid growth by replacing glucokinase with its higher affinity isoenzyme, hexokinase 2 (HK2), making HK2 an attractive drug target." (PMID 33594203, 2021).